SPRY2 (sprouty RTK signaling antagonist 2)
Diseases named in the same sentence as SPRY2 in open-access papers (continued):
Sharing a sentence is not in itself a finding about the gene and the disease.
prostate carcinoma (continued). "Indeed, SPRY2 promoter hypermethylation is correlated with decreased SPRY2 expression levels in several cancers, including hepatocellular carcinoma, B-cell lymphoma, endometrial carcinoma, and prostate cancer." (PMID 34685612, 2021). "Conversely, expression of a Spry2 gain-of-function transgene in the context of Pten homozygosity suppressed the AKT hyperactivation, and the prostate tumorigenesis resulted from Pten loss-of-function, implicating the Sprouty genes in regulation of ERK and PI3K/AKT pathways in prostate cancer." (PMID 24744103, 2014). "Likewise, loss of heterozygosity (LOH) of Spry2 on chromosome 13 has been found in prostate cancer, but not in other cancers." (PMID 21909357, 2011). "It was demonstrated before that simultaneous knockdown of Spry2 and PTEN results in higher pAkt activation than single knockdown of PTEN in prostate cancer tissue." (PMID 32038175, 2019). "Levels of SPRY2 and IL6 showed a significant inverse correlation in ADT‐treated prostate cancer patients with evidence of biochemical relapse (r = −0.427; P = 0.0261; n = 27; Fig EV4E)." (PMID 29540470, 2018). "Experimental models of prostate cancer have identified PTEN and SPRY2 as important molecular determinants of aggressive prostate carcinogenesis including metastases." (PMID 29540470, 2018). "Consistent with our previous reports on co‐occurrence of SPRY2 and PTEN alterations in prostate cancer, SPRY2 and PTEN levels significantly correlated in CRPC (Fig EV1C)." (PMID 29540470, 2018). "In many instances, SPRY2 isoform is downregulated, suggesting a possible tumor suppressor function in chronic lymphocytic leukemia CLL, non-small cell lung cancer NSCLC, hepatocellular carcinoma, breast cancer, and prostate cancer." (PMID 34685612, 2021).
hepatocellular carcinoma (16 papers, 2011 to 2024). A malignant tumor that arises from hepatocytes. "Our experiments demonstrated that the increase in miR-27a-3p in both hepatoma cells and macrophages resulted in a decrease in expression of SPRY2 at the protein level." (PMID 39742261, 2024). "According to previous reports, the reduction in SPRY2 levels in hepatoma cells promotes the proliferation and migration of hepatoma cells, and the decrease in SPRY2 levels in macrophages leads to the polarization of macrophages toward the M2 phenotype." (PMID 39742261, 2024). "Subsequently, immunohistochemical staining was used to evaluate the expression level of SPRY2 in hepatoma xenografts." (PMID 39742261, 2024). "A recent study also showed that miR-330-5p targets SPRY2 to promote hepatocellular carcinoma progression via MAPK/ERK signaling." (PMID 34306074, 2021). "Here, we demonstrate that in the human hepatoma cell line, Hep3B, the transcription of SPRY2 is inhibited by the transcription regulating hypoxia inducible factors (HIFs)." (PMID 28196140, 2017). "To investigate if HIF1α and HIF2α regulated SPRY2 mRNA and protein levels, we used siRNAs to silence the expression of endogenous HIF1α and HIF2α proteins in the hepatoma cell line Hep3B." (PMID 28196140, 2017). "Herein, we demonstrate that, in the hepatoma cell line Hep3B, endogenous HIF1α and HIF2α decreased the mRNA levels of SPRY2 with a concomitant decrease in the protein levels of Spry2." (PMID 28196140, 2017). "Two reports suggest that SPRY2 promoter is hypermethylated in hepatocellular carcinomas, but another report suggests otherwise." (PMID 28196140, 2017). "Among them, SPRY2 is reported to have a consistent repressive expression in malignant hepatocytes compared with normal or cirrhotic hepatocytes in human hepatocellular carcinoma where the MAPK activity is enhanced via multiple hepatocarcinogenic factors." (PMID 26121976, 2015). "One example is that microRNA hsa-miR-27a and gene PHB, SPRY2 are related with the same disease ‘hepatocellular carcinoma (DOID:684)’ by SIDD." (PMID 24146757, 2013). "Studies have shown that miR-21 regulates PTEN tumour suppressor in hepatocellular cancer cells and SPRY2 in cardiomyocytes." (PMID 21853131, 2011). "Moreover, miR-330-5p was confirmed to suppress SPRY2 to promote proliferation via MAPK/ERK signaling in hepatocellular carcinoma." (PMID 34158077, 2021). "SPRY2 is an important molecule for signal regulation in vivo, and the deletion of SPRY2 can lead to the activation of the PI3K/Akt/mTOR and MAPK/ERK signaling pathways, promote cell proliferation and migration, and lead to the development of hepatoma in vivo." (PMID 39742261, 2024). "Although showing the resemblance between the expression pattern of Spry2 and that of several potential tumor markers in hepatocellular carcinoma, the investigators ruled out loss of heterozygosity (LOH) or the promoter hypermethylation as possible mechanisms responsible for Spry2 downregulation." (PMID 24744103, 2014).
glioma (15 papers, 2012 to 2025). A benign or malignant brain and spinal cord tumor that arises from glial cells (astrocytes, oligodendrocytes, ependymal cells). "Sprouty homolog 2 (Spry2), which has been reported to be associated with invasive glioma, was identified as a novel target of miR-27b in U251 glioma cells, and the protein expression of Spry2 was negatively regulated by miR-27b in U251 cells." (PMID 25663918, 2015). "As Spry2 has previously been suggested to be associated with invasive glioma and miR-251 negatively regulated the Spry2 expression in U251 cells, it was speculated that miR-27b may also participate in the regulation of glioma U251 cell invasion." (PMID 25663918, 2015). "SPRY2 mRNA expression is upregulated in GB, and the upregulation of SPRY2 correlates with the glioma grade." (PMID 41516252, 2025). "Several in vitro and in vivo studies demonstrate that SPRY2 is an oncogene in GB as well, and high SPRY2 levels reduce survival of GB and glioma patients." (PMID 41516252, 2025). "Recent studies demonstrated that knockdown of SPRY2 enhances CD44 in cancer-associated fibroblasts, whereas knockdown of SPRY1 reduces stemness of patient-derived glioma stem cell spheres." (PMID 39682716, 2024). "On the other hand, low expression of Spry2 abolished the miR-27b inhibitory effect on glioma cell invasion." (PMID 35071748, 2022). "The Spry2 protein level was recently shown to be notably down-regulated in glioma patients with a more invasive tumor type, confirming the regulatory function of Spry2 in glioma invasion." (PMID 35071748, 2022). "Dis-inhibiting the ERK pathway by decreasing Spry2/4 levels does not only enhance reactive astrogliosis but appears to be an important mechanism to block glioma growth as well." (PMID 30225774, 2019). "PTEN negatively regulates miR-21 expression via the RNA-regulatory protein ribonuclease/angiogenin inhibitor 1 (RNH1), thereby preventing the downregulation of Spry2 by miR-21 in glioma cells." (PMID 32038175, 2019). "For example, in 54 of 166 RMPAhigh and in 30 of 168 RMPAlow gliomas from the TCGA mRNA-seq data set one genomic copy of SPRY2 was lost." (PMID 27385209, 2016). "In primary neurons and in C6 glioma cells, down‐regulation of Spry2 leads to the activation of Ras and ERK, whereas phosphorylation of Akt and p38 MAPK remains unchanged." (PMID 26540287, 2016). "Nevertheless, the expression of SPRY2 in these 54 RMPAhigh gliomas was on average 2-fold higher than in the 30 RMPAlow gliomas (p =3.2 × 10−6, t test)." (PMID 27385209, 2016). "Dysfunction of miR-27b and Spry2 has been found to be involved in the development and progression of glioma." (PMID 25663918, 2015). "Based on these data, it was suggested that miR-27b negatively regulated Spry2 expression at a post-transcriptional level in glioma U251 cells." (PMID 25663918, 2015). "The present study aimed to explore the roles of miR-27b and Spry2 in the regulation of glioma cell invasion." (PMID 25663918, 2015). "In the present study, it was revealed that overexpression of Spry2 significantly inhibited the invasion of glioma U251 cells." (PMID 25663918, 2015). "Previous studies have shown that miR-21 contributes to colon cancer and gliomas along with downregulation of SPRY2 to stimulate ERK signaling." (PMID 25303175, 2014). "Furthermore, miR-21 decreases the SPRY2 protein but enhances the resistance of SWOZ2 human glioma cells to carmustine (BCNU), an alkylating cytostatic for GB treatment." (PMID 41516252, 2025). "Furthermore, the overall survival of adult and pediatric glioma patients with high SPRY2 levels is reduced." (PMID 41516252, 2025). "Spry2 was verified as a new miR-27b target in glioma cell lines (U251), and the level of expression of Spry2 protein was inversely correlated with miR27b in glioma cells." (PMID 35071748, 2022). "The result of this study showed that miR-27b could directly inhibit the expression of Spry2 and increase glioma invasion." (PMID 35071748, 2022).
glioma (continued). "Furthermore, evidence shows that miR-21 increases the resistance of human glioma cells to carmustine (BCNU) by decreasing Sprouty RTK Signaling Antagonist 2 (Spry2) protein levels." (PMID 30583549, 2018). "In conclusion, the present study suggests that upregulation of miR-27b in glioma may promote glioma cell invasion by inhibiting the expression of its target, Spry2." (PMID 25663918, 2015). "Based on these data, it can be suggested that miR-27b may promote glioma cell invasion through direct inhibition of Spry2 expression." (PMID 25663918, 2015). "Additionally, inhibition of miR-27b and upregulation of Spry2 suppressed glioma cell invasion, while downregulation of Spry2 reversed the suppressive effect of miR-27b inhibition on glioma cell invasion." (PMID 25663918, 2015). "In addition, miR-27b was shown to regulate the protein expression of Spry2 by directly targeting the 3′UTR of Spry2 mRNA in glioma U251 cells." (PMID 25663918, 2015). "In addition, the present study identified Spry2 as a direct target of miR-27b, and demonstrated that the protein expression of Spry2 was negatively regulated by miR-27b in glioma U251 cells." (PMID 25663918, 2015). "Additionally, inhibition of Spry2 reversed the suppressive effect of miR-27b downregulation on glioma U251 cell invasion." (PMID 25663918, 2015). "The protein level of Spry2 has previously been reported to be significantly decreased in invasive glioma tissues, suggesting that Spry2 may participate in the regulation of glioma invasion." (PMID 25663918, 2015). "In addition, miR-27b suppression and Spry2 up-regulation both inhibited glioma cell invasion." (PMID 35071748, 2022). "In the present study, it was found that miR-27b played a promoting role in the regulation of glioma U251 cell invasion, and further molecular mechanism investigation suggested that the promotion of U251 cell invasion by miR-27b occurred partially by direct inhibition of Spry2." (PMID 25663918, 2015). "Furthermore, inhibition of miR-27b and upregulation of Spry2 could suppress glioma cell invasion, while downregulation of Spry2 reversed the suppressive effect of miR-27b inhibition on glioma cell invasion." (PMID 25663918, 2015). "However, to the best of our knowledge, the roles of and association between miR-27b and Spry2 have never been studied in glioma." (PMID 25663918, 2015). "Spry2 has previously been reported to be significantly downregulated in invasive glioma tissues, suggesting that Spry2 may participate in the regulation of glioma invasion." (PMID 25663918, 2015). "DYRK1A prevents endocytotic degradation of EGFR through phosphorylation of the EGFR-signaling modulator Sprouty 2 (SPRY2) and DYRK1A inhibition leads to reduced glioma growth." (PMID 34117217, 2021). "Up-regulation of miR-21 is triggered in glioma cells lacking functional phosphatase and tensin homolog (PTEN), but not in those harboring wild-type PTEN, and is responsible for glioma invasion by disrupting the negative feedback circuit of Ras/MAPK signaling mediated by Spry2." (PMID 23077620, 2012).
melanoma (15 papers, 2012 to 2025). A malignant, usually aggressive tumor composed of atypical, neoplastic melanocytes. "In a later study, microarray data validated by real-time PCR indicated upregulation of Spry2 in melanoma cell lines with mutations in BRAF and NRAS." (PMID 24744103, 2014). "Thus far, 8 out of 21 GLI targets we chose to validate—KRT16, S100A9, SOX9, BIRC7, EBI3, FLG, SAMMSON and SPRY2—were already implicated in melanoma pathogenesis." (PMID 36139698, 2022). "Neil Rosen’s group also clearly demonstrated that vemurafenib treatment of BRAF mutant melanoma cells caused receptor tyrosine kinase-mediated (RTK) activation of RAS via Spry2 downregulation, with CRAF activation and pERK rebound after initial profound inhibition." (PMID 32922659, 2020). "Previous reports have demonstrated Spry2 suppression promotes the development and progression of diverse cancers, including melanoma, lymphoma and gastric cancer." (PMID 37097161, 2023). "qPCR results show that SPRY2 is detected in all melanoma cell lines, especially those with GLI3 overexpression." (PMID 36139698, 2022). "Existing studies showed that SPRY2 inactivation promoted various cancer development and progression, such as melanoma, lymphoma, gastric cancer." (PMID 30464168, 2018). "Their genetic and gene expression analyses revealed that Spry2 is downregulated in melanoma cells harboring WT BRAF yet upregulated in the BRAFV600E mutants." (PMID 24744103, 2014). "Considering the wide-spread activating mutations in BRAF this observation was somewhat surprising especially as MAPK signal attenuation by Spry2 was suggested to be lost in melanoma cells harboring BRAFV600E." (PMID 22535842, 2012). "In addition, the genes EBI3, GH1, SOX9, RET, and SPRY2 are also good candidates for HH-GLI targets but exhibited a less uniform expression pattern in these melanoma cell lines." (PMID 36139698, 2022). "DEG analysis further revealed upregulation of genes SPRY2 (Bladder), and GAB2 (Non-small cell lung) and downregulation of genes CBL (Endometrial), TGFA (Melanoma) were associated with low survival rate and high risk of death as measured by survival probability and AUC score." (PMID 34764329, 2021). "Finally, SPRY2 (Bladder), CBL (Endometrial), TGFA (Melanoma) and GAB2 (Non-small cell lung) genes have high risk rate and low survival rate." (PMID 34764329, 2021). "In conclusion, they proposed that Spry2 may be bypassed in melanoma cells either by downregulation of its expression in WT BRAF cells or through BRAF mutation." (PMID 24744103, 2014). "After Survival Analysis we concluded that four genes (SPRY2-for Bladder cancer, CBL-for Endometrial cancer, TGFA-for Melanoma and GAB2 for Non-small cell lung cancer) were the Biomarkers for Nitroglycerin." (PMID 34764329, 2021). "In melanoma cells, ERK rebound upon BRAFV600E inhibition may be due to reduction of the ERK phosphatase DUSP6 and receptor tyrosine kinase blocker Spry2, which sequesters the Grb2:SOS complex, preventing the binding of receptor tyrosine kinase." (PMID 26023796, 2015). "To further validate the inverse correlation between MT1-MMP and SPRY proteins and to determine whether they are expressed in melanoma, we measured the expression levels of SPRY1, SPRY2 and SPRY4 in thirteen metastatic melanoma tumor samples." (PMID 26392417, 2015). "However, we also observed the downregulation of SPRY2 and 4 as well as SPRED1 and -2 in a melanoma cell line (451Lu) which is MEK inhibitor sensitive and does not display enhanced AKT activation by PD." (PMID 24970815, 2014). "Given widespread activating mutations in BRAF and, in particular, inability of Spry2 to attenuate ERK in the context of BRAFV600E mutation, their findings argue for a role of Sprouty in regulation of melanoma aggressiveness independent of attenuation of ERK." (PMID 24744103, 2014).
colon carcinoma (12 papers, 2012 to 2023). "They later reported downregulation of Spry2 in association with colon cancer progression and suggested a tumor suppressor role for Spry2." (PMID 24744103, 2014). "In order to investigate the 5mC status of SPRY2 in human colon cancers, DNA was extracted from 10 matched tumor and adjacent normal-appearing colonocytes and evaluated by COBRA." (PMID 34685612, 2021). "Identified, for the first time, SPRY2 transcript and protein upregulation is in concordance with promoter hypomethylation and increased 5hmC in colon cancers." (PMID 34685612, 2021). "It was previously shown that Spry2 plays a tumorigenic role in colon cancer via dysregulating tight junction and epithelial polarity factors, such as Patj1 and Llgl230,39,40." (PMID 33127892, 2020). "Collectively, data indicate that suppression of both SPRY1 and SPRY2 had additional effects that favor epithelial phenotype in colon cancer cells." (PMID 26434583, 2016). "Concurrent downregulation of SPRY1 and SPRY2 also increased E-cadherin and suppressed mesenchymal markers in colon cancer cells." (PMID 26434583, 2016). "Collectively, above results demonstrate that SPRY2 suppression by two different methods significantly upregulated miR-194-5p contents of colon cancer cells." (PMID 26434583, 2016). "We evaluated relative expression of SPRY1 and SPRY2 mRNA transcripts in human colon cancer tissues and adjacent controls by utilizing a colon cancer cDNA array." (PMID 26434583, 2016). "We identified that knockdown of SPRY2 expression increases miR-194-5p contents in colon cancer cells." (PMID 26434583, 2016). "We then investigated endogenous contents of miR-194-5p in three different colon cancer cell lines that express different levels of SPRY2." (PMID 26434583, 2016). "In vitro, Spry2 and E-cadherin exhibited an inverse correlation and reciprocal regulation in colon cancer cells." (PMID 24744103, 2014). "Accordingly, Spry2 expression was decreased with colon cancer disease progression, and re-expression increased PTEN levels and suppressed growth and migration." (PMID 22535842, 2012). "We therefore hypothesized that collectively, loss of 5mC in the SPRY2 promoter, along with increased 5hmC within SPRY2 promoter, might enhance SPRY2 expression in colon tumors that could promote oncogenic signals." (PMID 34685612, 2021). "SPRY2 is known to positively regulate MET levels in colon carcinoma, although it is unclear whether SPRY2 induces MET transcriptional activation or reduces MET degradation." (PMID 29445192, 2018). "Collectively, results indicate that SPRY2 may affect CRC metastasis in a positive manner and reduction of SPRY2 inhibits EMT in colon cancer cells." (PMID 26434583, 2016). "We further raised the question whether suppression of both SPRY1 and SPRY2 in colon cancer cells would exhibit a diverse effect on mesenchymal/EMT markers." (PMID 26434583, 2016). "Supplemented by a meta-analysis of the data available at the Oncomine database in favor of higher expression of Spry2 in colon tumors compared with other neoplasias, their results suggested a tumorigenic action and a potential role as a tumor marker for Spry2 in colon cancer." (PMID 24744103, 2014). "In line with earlier studies suggesting Sprouty genes as targets of miR-21, they proposed that Spry2 is negatively regulated by miR-21 and that such interaction may play a role in colon cancer carcinogenesis." (PMID 24744103, 2014). "Spry2 also suppressed the growth and tumorigenesis of colon cancer cells in vivo." (PMID 24744103, 2014). "By real-time quantitative RT-PCR on mRNA isolated from normal and tumor tissues of 67 patients with colon cancer, they showed that Spry2 was downregulated in 72.7 % (16/22) of stage II, 91.3 % (21/23) of stage III, and 100 % (22/22) of stage IV tumors examined." (PMID 24744103, 2014). "In addition, SPRY2 might serve as a potential biomarker with respect to anti-EGFR treatment response in colon cancers." (PMID 34685612, 2021).